IGF2 (insulin like growth factor 2)
Diseases named in the same sentence as IGF2 in open-access papers (continued):
Sharing a sentence is not in itself a finding about the gene and the disease.
cancer (continued). "IGF2BP3 is an oncofoetal protein synthesised de novo in cancer where it promotes drug resistance and metastasis via IGF2-dependent and IGF2-independent mechanisms through IGF1R RNA-binding." (PMID 40442778, 2025). "One of the first experiments using game theory in cancer research involved insulin-like growth factor II (IGF2)." (PMID 39774289, 2025). "Previous studies have highlighted the mutual involvement of NTRK1 and IGF2 in development and cancer." (PMID 40722704, 2025). "IR-A, commonly expressed in fetal and cancer cells, stimulates the proliferation of both epithelial and mesenchymal cells through insulin-like growth factor 2 (IGF2) binding." (PMID 40303997, 2025). "Transgenic models with persistent adult tissue-specific Igf2 overexpression led to localized overgrowth and/or cancer, uncovering autocrine and endocrine mechanisms of action." (PMID 40880432, 2025). "Three therapeutic monoclonal antibodies (AXL1717, MEDI-573, and BI836845) that neutralize IGF1/2 have the potential to counteract IGF2 repression of the immune reaction to cancer and its promotion of chemoresistance in cancer." (PMID 41007637, 2025). "IR-A has a greater affinity for IGF2 than does IR-B; the IR-A-IGF2 signaling loop is used by several cancer types to promote mitogenesis." (PMID 40303997, 2025). "IGF2BP2 belongs to the family of IGF2 RBPs, which are critical regulators of growth and development in various cancer types." (PMID 39948708, 2025). "In this study, we reported that the ASH1L/HIF-1α complex in invading cancer cells promotes IGF-2 expression, which triggers AKT-GSK3b-mTOR signaling and activates OXPHOS pathways in monocytes in the bone niche." (PMID 40394007, 2025). "The dysregulation of the PI3K/AKT/mTOR pathway in ASCC, driven by IGF2 from CAFs, highlights the potential of IGF2/IGF1R inhibitors as targeted treatments for this rare cancer." (PMID 40740483, 2025). "Insulin-like growth factors (IGF-1 and IGF-2) promote tumor growth and act as mitogens for colon mucosa, advancing cancer progression." (PMID 40806747, 2025). "- Preferentially binds IGF-2 and inhibits IGFs actions;- Increases cancer cell proliferation, survival and migration/invasion;- Regulates glucose homeostasis." (PMID 40723309, 2025). "IGF-1R, the receptor of IGF-2, is recognized as a promising target of cancer therapy, and monoclonal antibodies targeting human IGF-1R have been studied in clinical trials." (PMID 40394007, 2025). "For example, numerous studies documented protumorigenic effects of LOI of IGF2 in many cancer types." (PMID 40414875, 2025). "The increased expression of IR-A and an elevated IR-A: IR-B ratio facilitate the proliferative response of cancer cells to insulin and insulin-like growth factor 2 (IGF-2)." (PMID 38331804, 2024). "The proposed mechanism of action for the INS-IGF2 transcript in promoting cancer progression involves its action as a cis-acting regulation of the IGF2 gene, resulting in its overexpression." (PMID 39593106, 2024). "In the context of cancer, IGF-2 is often overexpressed in various tumors, contributing to tumor growth and progression." (PMID 39064802, 2024). "The implications of these findings indicate the promise of directing therapeutic interventions toward the insulin/IGF-2/IR-A pathway in the context of malignant tumors." (PMID 38331804, 2024). "Several studies have provided evidence to support that the insulin/IGF-2/IR-A pathway and its downstream signaling cascades serve as specific and distinct target sites in malignant tumors." (PMID 38331804, 2024). "In some cancer cells, four promoters (p0, p2, p3, and p4) whose IGF2 mRNA transcripts are imprinted contribute significantly to total IGF2 expression." (PMID 38812777, 2024). "Subsequently, given their plasma IGF2 levels, the patients with cancer were categorized into 3 groups." (PMID 39545420, 2024).
cancer (continued). "IGF2 serves as a key upstream factor driving fibroblast-mediated immunoevasion, positioning itself as a promising biomarker and target for cancer immunotherapy." (PMID 39545420, 2024). "Despite the highlighted differences between mouse and human Igf2/Mir483 regulation, our work has potential relevance to human imprinting syndromes, cancer, and genomic imprinting in general." (PMID 39283743, 2024). "Activation of the IGF2-Id1-IGF2 loop stimulates chronic aberrant IFN signaling in cancer cells, leading to a stem cell-like phenotype and chemotherapy resistance." (PMID 38887298, 2024). "In the autocrine/paracrine signaling loops of cancer cells, in particular, IGF2 working through IGF-1R and/or IR-A is frequently observed." (PMID 38542291, 2024). "Dysregulation of IGF-2 expression occurs in many other cancers, and IGF-2 is thought to stimulate cancer development via binding to IGF-1 receptors and subsequent activation of the MAPK and PI3-K/Akt pathways." (PMID 39372824, 2024). "We uncovered a notable increase of insulin-like growth factor 2 (IGF2) in immune-excluded tumors, predominantly secreted by cancer-associated fibroblasts (CAFs)." (PMID 39545420, 2024). "IGF2 LOI associated with hypermethylation of ICR1 and hypomethylation of IGF2 DMRs is prevalent and increases gene expression levels in the majority of cancers." (PMID 38812777, 2024). "AQP9 is downregulated by insulin-like growth factor 2 (IGF2), which is crucial for cancer stem cell stemness maintenance." (PMID 39125952, 2024). "High IGF2 expression is correlated with a poor prognosis and a lower immunotherapy response in patients with cancer." (PMID 39545420, 2024). "In these cell lines, IGF2 overexpression was one of the key signals for the cancer cell to maintain the tumorigenic features including proliferation and differentiation." (PMID 38542291, 2024). "Specifically, we analyzed pretreatment IGF2 levels in the plasma of a cohort consisting of 68 patients with cancer enrolled in a basket trial for anti–PD-1 treatment, encompassing individuals diagnosed with BRCA, COAD, and LUAD." (PMID 39545420, 2024). "IGFBP2 specifically can bind to insulin, IGF-1, and IGF-2 but binds with the highest affinity to IGF-2; however, it plays multiple roles in cancer in an IGF-independent manner." (PMID 39007351, 2024). "Specifically, the IGF family consisting of insulin, IGF-1, and IGF-2 regulates cellular functions relevant to cancer, including mediating the growth and survival of cancer cells (i.e., Akt and mechanistic target of rapamycin (mTOR) signaling)." (PMID 40443827, 2024). "In conclusion, in this work, we identified and elucidated a novel mechanism of resistance to oHSV therapy by which oHSV therapy induces cancer–TME cell communication via NFκB-dependent IGF2 expression and secretion." (PMID 38853689, 2024). "Since IGF2 LOI is already present in healthy tissues and increases cancer risk, it is possible that we detected too much cancer-associated LOI in “normal” samples to find significant differences in cancer." (PMID 39199324, 2024). "The selective growth inhibitory effect of 73 against hypoxia-adaptable cancer cells was initially attributed to the suppression of the insulin-like growth factor-2 (IGF-2) gene transcription, selectively induced under hypoxic conditions." (PMID 38667760, 2024). "Both IGF-1 and IGF-2 have demonstrated the ability to stimulate cancer cell proliferation and metastasis." (PMID 39301314, 2024). "To further elucidate the pivotal effect of IGF2 within CAFs, we cotransplanted CAFs with either control or shIgf2 constructs alongside various cancer cell lines into recipient mice." (PMID 39545420, 2024). "Moreover, S1P enhances insulin-like growth factor (IGF2) production and activity; this alteration was linked to an increased susceptibility of many carcinomas through IGF2-mediated promoting insulin growth factor 1 receptor (IGF1R) or hybrid receptors that may promote tumorigenesis." (PMID 38419070, 2024).
cancer (continued). "Variable cytoplasmic IGF-2 staining was initially reported between ACCs and ACAs and was considered a useful feature for diagnosing carcinomas." (PMID 38802933, 2024). "In particular, the IGF2BP2-driven IGF2-enhancing effect in cancer seems to be synergistically exerted by the parallel suppression of IGF2 signal inhibitors." (PMID 37371750, 2023). "Taken together, these studies suggest that peripheral hyperinsulinemia but also paracrine/autocrine IGF2 can favor immune evasion in certain cancers by upregulating the expression of immune checkpoint PD-L1." (PMID 36672737, 2023). "As a matter of fact, alterations in the autocrine loops IGF-2/IGF-1R often occur in human cancer, leading to the overactivation of the PI3K/AKT signaling pathway, which is responsible for impairment in cell proliferation and apoptosis." (PMID 36901760, 2023). "Local production of IGF-2 by epithelial and stromal cancer cells, along with an increased IR-A: IR-B ratio, supports the mitogenic response of cancer cells to insulin." (PMID 37834454, 2023). "A number of studies focusing on the role of IGF2 gene methylation and promoter usage in cancer have established the importance of IGF2 LOI status." (PMID 37371750, 2023). "Recent studies have implicated paracrine IGF2 in the induction and maintenance of epithelial–mesenchymal transition (EMT) and stem-like phenotype of cancer cells." (PMID 36672737, 2023). "For such reasons, inclusion of E2F3 in expression screening panels to identify and properly treat IGF2-driven cancers in adults has a proper rationale." (PMID 37371750, 2023). "Sustained IGF action promotes cancer development, as shown by transgenic animal models overexpressing IGF2." (PMID 36672737, 2023). "New aspects are emerging regarding the role of IGF2 in promoting cancer metastasis by promoting evasion from immune destruction." (PMID 36672737, 2023). "Additional studies are needed to clarify the role of C/EPB heterodimers towards IGF2 expression in cancer." (PMID 37371750, 2023). "In non-cancer cells, THC (20 μM) caused a reduction in the production of insulin-like growth factor 2 in human placental BeWo cells." (PMID 37946285, 2023). "Mechanistically, IGF1R blockade stimulated a STAT3-dependent increase in autocrine IGF2 production by cancer cells, which recruited macrophages and fibroblasts, leading to the production of CXCL8 and proangiogenetic and prometastatic actions." (PMID 36672737, 2023). "IGF2BPs are the object of an active area of investigation given their cancer-promoting effects extending beyond the ones mediated via IGF2 transcript binding." (PMID 37371750, 2023). "Both PLAG1 and PLAGL2 overexpression in cultured cells triggers IGF2 gene expression and induces cancer-promoting effects, including transformation." (PMID 37371750, 2023). "The “Proteoglycans in cancer” pathway was also exclusively enriched in AA-SScL fibroblasts, driven by the upregulation of IGF2, DCN, LUM, COL1A1, COL1A2, and the receptors KDR and TLR4." (PMID 36835058, 2023). "While IGF2 expression in somatic cells is regulated via parental imprinting, its regulation in cancer cells is determined by a combination of both imprinting and transcriptional regulation mechanisms reviewed elsewhere [, ibidem]." (PMID 38255147, 2023). "The molecular landscape provided at last strengthens the role of IGF2 in cancer initiation, progression and malignant phenotype maintenance." (PMID 37371750, 2023).
cancer (continued). "Provided that Wnt signaling is activated, overexpressed IGF2 moderately accelerates cancer development but is insufficient to initiate the progression of malignant tumors." (PMID 38269250, 2023). "Several lines of evidence suggest that autocrine IGF2 plays a role in promoting/maintaining stemness in cancer cells." (PMID 36672737, 2023). "IGF2 gene epigenetic regulation has been studied both during mammalian development as well as in IGF2-overexpressing syndromes and cancer." (PMID 37371750, 2023). "IR-A is a dual high-affinity receptor for insulin and IGF2 and represents the principal receptor for IGF2 in those cancers with IR-A overexpression." (PMID 36672737, 2023). "Regarding micro RNAs, upregulation of microRNA 615, also identified as an ACC biomarker, was found to regulate several cancer pathways, and importantly was found to inhibit IGF2 in several cancer types (Godínez-Rubí and Ortuño-Sahagún, 2020)." (PMID 38028548, 2023). "In this study, we found that the transfer of exosomal IGF-2 from dormant cancer cells into stromal cells increased the glycolysis of stromal cells." (PMID 36568212, 2022). "IGF2, a prosurvival factor which is usually employed by cancer cells in response to different stressful stimuli, was repressed by loss of FOXA1 but upregulated by gain of FOXA1." (PMID 35974000, 2022). "Our data outline SSO55 induced inhibition of cancer hallmarks, a future therapeutic strategy for using IR-B promoting SSOs in combination with existing IGF-2 therapies for the treatment of RMS patients." (PMID 35017650, 2022). "Biallelic expression of IGF2 is frequently observed in cancers due to DNA methyltransferase 1 (DNMT1)-mediated de novo methylation of the ICR, a process called loss of imprinting (LOI)." (PMID 35974000, 2022). "Functional investigations indicated that this circRNA blocks apoptotic cell death and promotes in vivo cancer growth via regulating the miR-665/insulin growth factor 2 (IGF2) axis." (PMID 35055115, 2022). "Dormant cancer cell-derived exosomes reprogrammed the metabolic process of BMSCs through transferring exosomal IGF-2 and IGFBP2." (PMID 36568212, 2022). "Drugs that block IGF2 and decrease glucose levels, such as metformin, have become a promising approach to prevent and treat cancer." (PMID 35391781, 2022). "ZKSCAN3 enhances the expression of a variety of target genes involved in cancer cell proliferation (cyclin D2), growth (IGF-2, integrin β4), metastasis (MMP26), and angiogenesis (VEGF)." (PMID 36012568, 2022). "A similar developmental trend is exhibited by IGF2, which is produced by most cancer cells and, usually, constitutes the main ligand in tumors." (PMID 36479090, 2022). "IGF-2 also plays roles in several cancers, such as breast, prostate and colorectal, by promoting cell growth and survival in humans." (PMID 35681494, 2022). "In cancer research, researchers have found that IGF-2 is overexpressed in many cancer types, as well as its receptors." (PMID 36358907, 2022). "Their co-overexpression in various cancers has been confirmed, and their co-expression in rectal cancer makes miR-483-5P a possible molecular chaperone of IGF-2." (PMID 36358907, 2022). "The emerging evidence has proposed the oncofetal IGF2 mRNA binding protein 1 (IGF2BP1) as the cancer turnover regulator for its pivotal role in stabilizing the pro-oncogenic mRNA expression." (PMID 36536402, 2022). "When relevant, the roles of IGF1 and IGF2 in cancer biology will be compared to those of the closely related insulin molecule." (PMID 36479090, 2022). "IGF2BP2 and IGF2BP3, members of the mammalian IGF2 mRNA-binding protein family, were found correlated with an overall poor prognosis and metastasis of various cancer." (PMID 34332578, 2021).
cancer (continued). "PDE4D silencing/inhibition also affected the gene expression of several cancer-related genes, such as the pro-oncogenic insulin growth factor (IGF2), which is down-regulated." (PMID 34062786, 2021). "Considering that IR-A is also a high affinity receptor for IGF-2, this isoform displays oncogenic properties providing a selective growth advantage to cancer cells." (PMID 34445431, 2021). "Some researches hold that IGF2 participated in the regulation of the cancer cell secretion of VEGF and further impacted the power of VEGFA antibody." (PMID 33582655, 2021). "Evidence shows that targeting either IGF2 or its receptor IGF1R blocks cancer progression and displays significant antitumor activity." (PMID 33407516, 2021). "IGF-1R is the receptor for both IGF-1 and IGF-2, and several oncogenes targeting IGF-1R transcription have been reported to cause the overexpression of IGF-1R in cancers." (PMID 33669204, 2021). "There are several SNPs in IGF2 that have been previously reported to have a role in cancer or other diseases; such as rs1004446." (PMID 35095996, 2021). "The suggested reasons consist in the enhancer role of 17β-estradiol on adrenocortical cell proliferation, in the increased estrogen-related receptor α expression in cancer tissues and insulin-like growth factor 2 stimulation of ACC cell proliferation." (PMID 33807024, 2021). "Among many biomarkers of cancer, IGF-2 and IGFBP-2 expression is upregulated in many types of cancer and is associated with an increased risk of developing cancers therefore frequently considered as neoplastic marker." (PMID 34899612, 2021). "Impeding the IGF2 pathway by reducing IN-RA expression (targeting the exon-11-skipped IN-RA isoform) and consequently mitigating cancer cell proliferation, migration, and angiogenesis." (PMID 34769221, 2021). "IGF2BP3 is a member of the IGF2 mRNA binding protein family—also known as the m6A binding protein—which exerts its biological functions in various human cancers." (PMID 34802443, 2021). "IGF-1 encourages longitudinal bone growth, and both IGF-1 and IGF-2 take part in cancer progression." (PMID 34501405, 2021). "CAF-derived soluble factors including IL6, IL17A, IGF1, IGF2, and nitric oxide indirectly can mediate the development of cancer treatment resistance." (PMID 32932015, 2021). "LXY6090 reduces the level of HIF-1α target genes, such as VEGF and insulin-like growth factor 2 (IGF2), in vitro and the growth of cancer in vivo." (PMID 34575983, 2021). "The molecular mechanism behind this phenomenon was ascribed to a ZFP57-regulated imprinted gene, Insulin-like Growth Factor 2 (IGF2), which is known for its involvement in the development of various cancers." (PMID 33672287, 2021). "On the other hand, downregulation of IGF-IR induces a switch resulting in enhanced IGF-2/IR-A signaling in cancer." (PMID 34069554, 2021). "Recently published data support the impact of circRNA/IGF2 interaction in modulating cancer cell metabolism." (PMID 33673232, 2021). "IGF2 and anti-apoptotic gene KRT1 were significantly overexpressed in MTIs- resistant cancer cells, and exhaustion of IGF2 can restore paclitaxel sensitivity." (PMID 33221769, 2020). "IGF-2 also increases insulin receptor/IGF 1 receptor (IGF1R) axis activation in cancer cells to enhance resistance to anti-EGFR-targeted therapy in cholangiocarcinoma." (PMID 33553157, 2020). "Patients with 11p15 telomeric domain defects (H19/IGF2:IG-DMR -GOM and UPD) have a higher risk of developing cancer compared to cases presenting centromeric aberrations (KCNQ1OT1:TSS-DMR-LOM mutation and CDKN1C)." (PMID 33101381, 2020). "IGF2 is an effective predictor of cancer risks as its over-expression occurred in many cancers and was associated with a poor prognosis." (PMID 32372053, 2020).